KAT2A (lysine acetyltransferase 2A)
Description:
Protein lysine acyltransferase that catalyzes acetylation of histone and non-histone proteins using acetyl-CoA. Also catalyzes acyl-CoA-dependent acylation of lysine residues in proteins using alternative acyl-CoA donors, including propionyl-CoA, butyryl-CoA, succinyl-CoA, glutaryl-CoA, crotonyl-CoA and lactoyl-CoA. Acts as a histone lysine succinyltransferase: catalyzes succinylation of histone H3 on 'Lys-79' (H3K79succ), with a maximum frequency around the transcription start sites of genes. Succinylation of histones gives a specific tag for epigenetic transcription activation. Association with the 2-oxoglutarate dehydrogenase complex, which provides succinyl-CoA, is required for histone succinylation. In different complexes, functions either as an acetyltransferase (HAT) or as a succinyltransferase: in the SAGA and ATAC complexes, acts as a histone acetyltransferase. Has significant histone acetyltransferase activity with core histones, but not with nucleosome core particles. Has a a strong preference for acetylation of H3 at 'Lys-9' (H3K9ac). Also catalyzes acetylation of histone H1.4 (H1-4) at 'Lys-34' (H1.4K34ac), a modification enriched at promoters of active genes. Acetylation of histones gives a specific tag for epigenetic transcription activation. Recruited by the XPC complex at promoters, where it specifically mediates acetylation of histone variant H2A.Z.1/H2A.Z, thereby promoting expression of target genes. Involved in long-term memory consolidation and synaptic plasticity: acts by promoting expression of a hippocampal gene expression network linked to neuroactive receptor signaling (By similarity). Acts as a positive regulator of T-cell activation: upon TCR stimulation, recruited to the IL2 promoter following interaction with NFATC2 and catalyzes acetylation of histone H3 at 'Lys-9' (H3K9ac), leading to promote IL2 expression (By similarity). Required for growth and differentiation of craniofacial cartilage and bone by regulating acetylation of histone H3 at 'Lys-9' (H3K9ac) (By similarity). Regulates embryonic stem cell (ESC) pluripotency and differentiation (By similarity). Also acetylates non-histone proteins, such as CEBPB, MRE11, PPARGC1A, PLK4 and TBX5. Involved in heart and limb development by mediating acetylation of TBX5, acetylation regulating nucleocytoplasmic shuttling of TBX5. Acts as a negative regulator of centrosome amplification by mediating acetylation of PLK4. Acts as a negative regulator of gluconeogenesis by mediating acetylation and subsequent inactivation of PPARGC1A. Also acts as a histone glutaryltransferase: catalyzes glutarylation of histone H4 on 'Lys-91' (H4K91glu), a mark that destabilizes nucleosomes by promoting dissociation of the H2A-H2B dimers from nucleosomes. Catalyzes histone H3 lactylation at 'Lys-14' and 'Lys-18' in a lactyl-CoA-dependent manner. Lactyl-CoA for this reaction can be generated by ACSS2. (Microbial infection) In case of HIV-1 infection, it is recruited by the viral protein Tat. Regulates Tat's transactivating activity and may help inducing chromatin remodeling of proviral genes.
Synonyms: hGCN5; GCN5; GCN5L2; PCAF-b
Tractability: Small molecule: a structure with a bound ligand is known; a high-quality ligand is known; it has a high-quality binding pocket. PROTAC: it is named in the literature on targeted protein degradation; UniProt records ubiquitination sites on it; ubiquitination databases record sites on it; its protein half-life has been measured; a small molecule that binds it is known.
Target class: Writer; Histone acetyltransferase; GNAT family; Epigenetic regulator
Chemical probes: GSK4027 (high quality), L-Moses (high quality), L-Moses
Gene: Protein-coding gene on chromosome 17 (42,113,111 to 42,121,382, reverse strand). Ensembl gene ENSG00000108773.
Subcellular location: Nucleus; Chromosome; Cytoplasm, cytoskeleton, microtubule organizing center, centrosome
Pathways (Reactome):
Gene expression (Transcription): B-WICH complex positively regulates rRNA expression; Formation of WDR5-containing histone-modifying complexes; Notch-HLH transcription pathway; RNA Polymerase I Transcription Initiation; RUNX3 regulates NOTCH signaling
Developmental Biology: Cardiogenesis; Differentiation of naive CD4+ T cells to T helper 2 cells (Th2 cells); Formation of paraxial mesoderm; Regulation of gene expression in late stage (branching morphogenesis) pancreatic bud precursor cells
Signal Transduction: NOTCH1 Intracellular Domain Regulates Transcription; NOTCH3 Intracellular Domain Regulates Transcription; NOTCH4 Intracellular Domain Regulates Transcription; Pre-NOTCH Transcription and Translation
Disease: Constitutive Signaling by NOTCH1 HD+PEST Domain Mutants; Constitutive Signaling by NOTCH1 PEST Domain Mutants
Chromatin organization: HATs acetylate histones
Metabolism of proteins: Ub-specific processing proteases
Gene Ontology:
Molecular function: acetyltransferase activity; chromatin binding; DNA-binding transcription factor binding; histone acetyltransferase activity; histone deacetylase binding; histone glutaryltransferase activity; histone H1-4K34 acetyltransferase activity; histone H3 acetyltransferase activity; histone H3K9 acetyltransferase activity; histone succinyltransferase activity; peptide glutaryltransferase activity; protein binding; protein N-acyltransferase activity; protein-lysine-acetyltransferase activity; transcription coactivator activity; acyltransferase activity, transferring groups other than amino-acyl groups; peptide butyryltransferase activity; peptide crotonyltransferase activity; peptide lactyltransferase (CoA-dependent) activity; protein phosphatase binding; protein propionyltransferase activity
Biological process: antiviral innate immune response; internal peptidyl-lysine acetylation; negative regulation of centriole replication; negative regulation of gluconeogenesis; negative regulation of SCF-dependent proteasomal ubiquitin-dependent catabolic process; negative regulation of transcription by RNA polymerase II; peptidyl-lysine glutarylation; positive regulation of cGAS/STING signaling pathway; positive regulation of DNA-templated transcription; positive regulation of transcription by RNA polymerase II; protein localization to plasma membrane; regulation of cell cycle; regulation of cell division; regulation of DNA-templated transcription; regulation of protein stability; regulation of transcription by RNA polymerase II; regulation of tubulin deacetylation; chromatin remodeling; heart development; limb development; long-term memory; positive regulation of cytokine production; regulation of bone development; regulation of cartilage development; regulation of DNA repair; and 13 more
Cellular component: ATAC complex; centrosome; chromosome; cytoplasmic side of plasma membrane; extracellular region; histone acetyltransferase complex; nucleus; oxoglutarate dehydrogenase complex; SAGA complex; transcription factor TFTC complex; mitotic spindle; nucleoplasm; chromatin
Genetic constraint (gnomAD): Loss-of-function variants: 39 observed, 86.75 expected, observed/expected ratio (o/e) 0.45, 90% interval 0.35 to 0.59. The upper end of that interval is the gene's LOEUF score, 0.59, which puts it in group 2 of 6, group 1 being the genes least tolerant of losing a copy. Missense variants: 681 observed, 1,013.3 expected, observed/expected ratio (o/e) 0.67, 90% interval 0.63 to 0.72. Synonymous variants: 404 observed, 404.36 expected, observed/expected ratio (o/e) 1, 90% interval 0.92 to 1.09.
Homologues: Orthologues: chimpanzee KAT2A (99% identical), macaque RAB5C (99% identical), pig KAT2A (99% identical), dog KAT2A (98% identical), rat Kat2a (98% identical), mouse Kat2a (97% identical), rabbit KAT2A (93% identical), guinea pig KAT2A (86% identical), tropical clawed frog kat2a (81% identical), zebrafish kat2a (81% identical), Caenorhabditis elegans baz-2 (12% identical), Drosophila melanogaster Acf (11% identical). Paralogues in human: KAT2B (69% identical), BPTF (29% identical), BAZ2B (14% identical), BAZ2A (13% identical), BAZ1B (12% identical), BAZ1A (11% identical), BRD2 (9% identical), BRD4 (9% identical), BRD3 (8% identical), BRDT (8% identical), CECR2 (8% identical).
Diseases named in the same sentence as KAT2A in open-access papers:
KAT2A is named in the same sentence as 85 diseases in open-access papers, as found by Europe PMC text mining. Sharing a sentence is not in itself a finding about the gene and the disease. The quoted sentences say what the papers report.
breast cancer (14 papers, 2010 to 2026). A primary or metastatic malignant neoplasm involving the breast. "We detect evidence of this palmitoylation-induced regulation of KAT2A in lung metastasis samples from patients with breast cancer." (PMID 41826695, 2026). "In breast cancer, KAT2A‐mediated RCC2 lactylation at K124 facilitates RCC2 recruitment of SERBP1, stabilizing MAD2L1 mRNA and promoting progression." (PMID 41454479, 2026). "We discovered that KAT2A expression is regulated by palmitoylation in breast cancer-derived metastases." (PMID 41826695, 2026). "We observed that STAT3 expression had the strongest positive correlation with KAT2A expression in metastatic breast cancer patients (R=0.74, p <0.001)." (PMID 41826695, 2026). "KAT2A induced EMT in breast cancer cells by activating the transforming growth factor-β (TGF-β)/Smad pathway, and inhibition of KAT2A reduced the survival, migration, and invasion of MDA-MB-231 cells in vitro." (PMID 40165290, 2025). "We further show that breast cancer cells rely on CPT1a for fatty acid oxidation, which in turn activates NF-κB signaling via the acetylation of p65 in a KAT2a-dependent manner." (PMID 36732635, 2023). "Compared to benign neoplasia and normal breast samples, breast cancer samples had high expression levels and/or amplification of KAT2A." (PMID 36476410, 2022). "Additionally, we found that a DDR1 signature GSVA score was positively correlated with KAT2A expression in metastases from breast cancer patients." (PMID 41826695, 2026). "Moreover, KAT2A expression was significantly correlated with a STAT3 activity signature based on the GSVA analysis across metastatic breast cancer patients." (PMID 41826695, 2026). "Therefore, we concluded that this provides evidence for the palmitoylation-induced KAT2A activity via STAT3 in breast cancer patients with lung metastases." (PMID 41826695, 2026). "KAT2A could promote leukemia stem-like cell propagation or regulate the tamoxifen resistance in breast cancer." (PMID 34268311, 2021). "KAT2B, EP300, KAT6A (MYST family), and KAT2A (GNAT family) are recruited to ER-responsive promoters and are critical for estrogen-dependent proliferation of ER-positive breast cancer cells." (PMID 40165290, 2025). "We therefore collected several metastatic lesions of different organs from two patients with breast cancer within the UPTIDER rapid autopsy program and determined CPT1a and KAT2a protein expression." (PMID 36732635, 2023). "In line, Stat3 silencing abrogated palmitate-induced KAT2A gene and protein expression and spheroid growth in 4T1, and human MCF7, HCC70 and MCF10A H-RasV12 breast cancer cells." (PMID 41826695, 2026). "Therefore, we collected lung metastasis tissues from four patients with breast cancer within the UPTIDER rapid autopsy program 28 and determined DHHC20 protein expression, STAT3 phosphorylation and KAT2A protein expression." (PMID 41826695, 2026).
leukemia (11 papers, 2016 to 2024). A malignant (clonal) hematologic disorder, involving hematopoietic stem cells and characterized by the presence of primitive or atypical myeloid or lymphoid cells in the bone marrow and the blood. "At a cellular level, loss of Kat2a results in perturbation of leukemia lineage trajectories, with emergence of multiple incongruent differentiation pathways that deplete LSC but fail to uniformly differentiate leukemia cells." (PMID 35921412, 2022). "Taken together, the data indicate that regulation of the translational machinery at least partially mediates the imbalance between self-renewal and differentiation observed in MLL-AF9-driven leukemia upon Kat2a loss." (PMID 31985402, 2020). "Compatible with these observations, Kat2a loss in the context of MLL-AF9 leukemia impacted H3K9ac specifically at gene promoters." (PMID 31985402, 2020). "The experiments showed that the loss of Kat2a delayed the development of leukaemia in the mice and progressively depleted leukaemia stem cells, causing the disease to become less aggressive." (PMID 31985402, 2020). "Somewhat surprisingly, the list of target promoters failed to include most MLL-AF9 ChIP targets with the leukemia self-renewal associated Hox gene signature, namely Hoxa9, Hoxa10 and Meis1, escaping Kat2a-dependent promoter acetylation control." (PMID 31985402, 2020). "S5, A and B) to identify differences in transcriptional states that accompany loss of Kat2a and may help explain Kat2aNULL advantage in leukemia progression." (PMID 35921412, 2022). "Kat2a loss depletes functional MLL-AF9 leukemia stem-like cells." (PMID 31985402, 2020). "Kat2a loss impairs establishment of MLL-AF9 leukemia in vivo." (PMID 31985402, 2020). "Loss of Kat2a increases cell-to-cell variability in transcription at all levels of mean gene expression, which is reflected in poor coordination in gene expression programs in Kat2a KO leukemia cells." (PMID 31985402, 2020). "Loss of Kat2a increases transcriptional heterogeneity of primary MLL-AF9 leukemias." (PMID 31985402, 2020). "Proscillaridin A induced a rapid loss of MYC protein expression in MYC-driven leukemia cells through the downregulation of series of KATs (KAT2A, KAT3A, KAT3B, KAT5 and KAT6A) known to be involved in MYC protein stability (by lysine acetylation) and activation of MYC transcriptional programs." (PMID 31196146, 2019). "Nevertheless, secondary leukemias displayed an increased proportion of early (Mac1+Gr1-), but not late (Mac1+Gr1+) differentiated myelo-monocytic cells, suggesting that loss of Kat2a may perturb self-renewal and differentiation progression at multiple levels." (PMID 31985402, 2020). "We reckoned that loss of Kat2a affected the probability of leukemia development through dysregulation of transformed cells, and sought to probe this hypothesis by investigating the transcriptional programs of WT and KO leukemias at the single-cell level." (PMID 31985402, 2020). "This was likely due to the functional consequence of reduced translation in a subset of Kat2a knockout cells, which negatively impacted leukaemia stem cell maintenance/disease progression." (PMID 39560103, 2024). "Kat2a, a histone acetyl transferase, reduces transcriptional noise, decreasing heterogeneity in a mouse leukaemia stem cell model." (PMID 39560103, 2024). "Kat2a loss (NULL) results in enhanced cell-to-cell transcriptional variability and progressive loss of leukemia stem cells (LSCs) transformed with the KMT2A-MLLT3 (MLL-AF9) gene fusion." (PMID 35921412, 2022). "Accordingly, MLL-AF9 leukemia knockout for Kat2a displayed enhanced noise specifically in translation-associated genes, which was accompanied by reduced protein synthesis and associated with depletion of leukemia stem-like cells." (PMID 35921412, 2022).
leukemia (continued). "These latest observations mirror our previously identified role for Kat2a in maintenance of established leukemia stem-like cells and suggest that Kat2a plays stage-specific roles during leukemogenesis, which are preserved across leukemia models." (PMID 35921412, 2022). "Loss of Kat2a led to a marked decrease in survival of RT1(9a) recipient animals, compatible with accelerated leukemia progression." (PMID 35921412, 2022). "Ribosome biosynthetic and translation factor genes are pervasive targets of KAT2A, and our data suggest that destabilization of translation acts to facilitate transformation at least transiently and down-regulation of translation-associated genes may accompany preleukemia to leukemia progression." (PMID 35921412, 2022). "In this study, we have shown that Kat2a loss facilitates preleukemia progression in Idh1R132H and RUNX1-RUNX1T1(9a) mouse models of human disease, with acceleration of frank leukemia onset in the case of RT1(9a)." (PMID 35921412, 2022). "(F) Distribution of burst sizes for the Robust gene set in Kat2a WT and KO primary leukemias, as calculated by the D3E algorithm." (PMID 31985402, 2020). "(E) Distribution of burst frequencies for the Robust gene set in Kat2a WT and KO primary leukemias, as calculated by the D3E algorithm." (PMID 31985402, 2020). "(B) Relative expression (quantitative RT-PCR) of Kat2a in MLL-AF9 primary leukemia BM cells from Kat2a WT and KO backgrounds, mean ± SEM, n = 3, **p<0.001, 2-tailed t-test." (PMID 31985402, 2020). "Kat2a KO recipient animals had a moderate advantage in survival, suggesting a protracted development of leukemia." (PMID 31985402, 2020). "In summary, loss of Kat2a depletes functional LSC and alters cellular hierarchies within MLL-AF9 leukemia." (PMID 31985402, 2020). "Leukemias were nevertheless depleted of Kat2a expression, thus excluding selection of escapee cells." (PMID 31985402, 2020). "(E) Flow cytometry analysis of BM cells from secondary Kat2a WT and KO leukemia transplant recipients (50K and 5 K cells)." (PMID 31985402, 2020). "(C) Extreme Limiting Dilution Analysis of leukemia-initiating cell frequency in Kat2a WT and KO primary leukemias." (PMID 31985402, 2020). "Through combined chromatin profiling and single-cell transcriptomics of a conditional knockout mouse, we demonstrate that Kat2a contributes to leukemia propagation through preservation of leukemia stem-like cells." (PMID 31985402, 2020). "We then tested the effect on emergent protein synthesis in mouse MLL-AF9 leukemias by quantifying OP-Puro incorporation in Kat2a WT and KO phenotypic L-GMP." (PMID 31985402, 2020). "The exception are the central clusters 11 and 12, which have minimal representation in Kat2a KO leukemia." (PMID 31985402, 2020). "Significantly, the level of Kat2a gene expression knockout was profound and retained in secondary leukemias, similar to the primary leukemias they originated from." (PMID 31985402, 2020). "We identified promoters as H3K4 tri-methyl (me3) peaks and enhancers with H3K4 mono-methyl (me1)- enriched regions and inspected the respective pattern of distribution of H3K9ac in pooled MLL-AF9 primary leukemias initiated by Kat2a KO or WT cells." (PMID 31985402, 2020). "(B) Top ENCODE ChIP-seq Significance Tool enrichments for H3K9ac-positive promoters exclusive to Kat2a WT primary MLL-AF9 leukemia cells." (PMID 31985402, 2020). "The increase in gene expression CV associates with greater cell-to-cell dispersion, in other words reduced cell-to-cell correlation in transcript levels, amongst Kat2a KO leukemia cells." (PMID 31985402, 2020). "Future studies directing Kat2a catalytic activity to single or multiple loci will illuminate individual vs. global target gene contributions to the leukemia phenotype." (PMID 31985402, 2020). "We performed ChIP-qPCR analysis of Myc and Gabpa binding at promoter peaks depleted of H3K9ac binding in Kat2a KO leukemias." (PMID 31985402, 2020).